OR10H2 (olfactory receptor family 10 subfamily H member 2)
Description:
Odorant receptor.
Tractability: Antibody: its Gene Ontology location is reachable by antibodies, with high confidence; UniProt places it where antibodies can reach, with medium confidence; UniProt predicts a signal peptide or a membrane-spanning region.
Gene: Protein-coding gene on chromosome 19 (15,728,024 to 15,729,052, forward strand). Ensembl gene ENSG00000171942.
Subcellular location: Cell membrane
Pathways (Reactome):
Sensory Perception: Expression and translocation of olfactory receptors; Olfactory Signaling Pathway
Gene Ontology:
Molecular function: olfactory receptor activity; G protein-coupled receptor activity
Biological process: detection of chemical stimulus involved in sensory perception of smell; G protein-coupled receptor signaling pathway
Cellular component: plasma membrane; membrane
Genetic constraint (gnomAD): Loss-of-function variants: 2 observed, 1.46 expected, observed/expected ratio (o/e) 1.37, 90% interval 0.44 to 1.92. That is too few expected variants to judge how well the gene tolerates losing a copy. Missense variants: 355 observed, 410.52 expected, observed/expected ratio (o/e) 0.86, 90% interval 0.79 to 0.94. Synonymous variants: 204 observed, 176.98 expected, observed/expected ratio (o/e) 1.15, 90% interval 1.03 to 1.29.
Homologues: Orthologues: mouse Or10h1 (84% identical), rat Or10h1 (84% identical), mouse Or10h1b (83% identical), rat Or10h1d (83% identical), rat Olr1093 (83% identical), mouse Or10h5 (82% identical), rat Olr1092 (82% identical), rat Olr1090 (82% identical). Paralogues in human: OR10H1 (88% identical), OR10H5 (87% identical), OR2K2 (47% identical), OR10A5 (46% identical), OR10C1 (45% identical), OR13D1 (45% identical), OR2S2 (45% identical), OR10AG1 (44% identical), OR10A2 (44% identical), OR10A4 (44% identical), OR10A7 (43% identical), OR13C4 (43% identical), and 80 more.
Diseases named in the same sentence as OR10H2 in open-access papers:
OR10H2 is named in the same sentence as 2 diseases in open-access papers, as found by Europe PMC text mining. Sharing a sentence is not in itself a finding about the gene and the disease. The quoted sentences say what the papers report.
acute myeloid leukemia (1 paper, 2023). Acute myeloid leukemia (AML) is a group of neoplasms arising from precursor cells committed to the myeloid cell-line differentiation. "Gene OR10H2 located in locus 19p13.12 and gene STX18-AS1 in locus 4p16.2 are associated with acute myeloid leukemia and congenital heart disease, and the SNPs that have been associated to DKD are rs11664515 (p = 2.27 × 10–6) and rs16836018 (p = 2.27 × 10–6), respectively." (PMID 36949158, 2023).
OR10H2 also shares sentences with these, for which no sentence is quoted: congenital heart disease (1 paper).